VSTM2B (V-set and transmembrane domain containing 2B)
Tractability: Antibody: UniProt predicts a signal peptide or a membrane-spanning region.
Gene: Protein-coding gene on chromosome 19 (29,524,739 to 29,564,553, forward strand). Ensembl gene ENSG00000187135.
Subcellular location: Membrane
Gene Ontology:
Cellular component: membrane
Genetic constraint (gnomAD): Loss-of-function variants: 26 observed, 22.31 expected, observed/expected ratio (o/e) 1.17, 90% interval 0.85 to 1.61. The synonymous counts are far from expectation, so gnomAD's model fits this gene poorly and the ratio says little. Missense variants: 399 observed, 367.62 expected, observed/expected ratio (o/e) 1.09, 90% interval 1 to 1.18. Synonymous variants: 226 observed, 180.01 expected, observed/expected ratio (o/e) 1.26, 90% interval 1.13 to 1.4.
Homologues: Orthologues: chimpanzee VSTM2B (99% identical), macaque VSTM2B (96% identical), guinea pig VSTM2B (92% identical), rabbit VSTM2B (91% identical), pig VSTM2B (91% identical), mouse Vstm2b (89% identical), rat Vstm2b (87% identical), dog VSTM2B (77% identical), tropical clawed frog vstm2b (60% identical), zebrafish vstm2b (51% identical). Paralogues in human: CXADR (18% identical), IGSF11 (17% identical), ESAM (16% identical), GPA33 (15% identical), MXRA8 (15% identical), VSIG1 (15% identical), VSIG2 (15% identical), JAM3 (15% identical), CLMP (14% identical), VSIG8 (14% identical), F11R (14% identical), JAM2 (13% identical), and 2 more.
Diseases named in the same sentence as VSTM2B in open-access papers:
VSTM2B is named in the same sentence as 8 diseases in open-access papers, as found by Europe PMC text mining. Sharing a sentence is not in itself a finding about the gene and the disease. The quoted sentences say what the papers report.
ataxia telangiectasia (1 paper, 2016). Ataxia-telangiectasia is the association of severe combined immunodeficiency (affecting mainly the humoral immune response) with progressive cerebellar ataxia. "For some of the candidates, no commercial antibodies have been developed, resulting in limited information about their distribution and concentration in the brain tissues or CSF (for example, VSTM2B protein previously linked to pathogenesis of ataxia telangiectasia)." (PMID 27186164, 2016).
delirium (1 paper, 2023). A disorder characterized by confusion; inattentiveness; disorientation; illusions; hallucinations; agitation; and in some instances autonomic nervous system overactivity. "A CSF proteomic study found that lower preoperative levels of transmembrane domain-containing protein 2B (VSTM2B) and coagulation factor V (FA5) were positively correlated with delirium severity." (PMID 37251808, 2023).
frontotemporal dementia (1 paper, 2020). Frontotemporal dementia (FTD) comprises a group of neurodegenerative disorders, characterized by progressive changes in behavior, executive dysfunction and language impairment, as a result of degeneration of the medial prefrontal and frontoinsular cortices. "Another recent study used proteomics to identify CSF biomarkers in genetic frontotemporal dementia, and found that symptomatic granulin mutation carriers had significantly lower levels of VSTM2B than both non-carriers and presymptomatic carriers." (PMID 32194463, 2020).
tumour (2 papers, 2012 to 2017). "VSTM2B expression was undetected in any of the tumours analysed." (PMID 22433433, 2012).
adenocarcinoma (1 paper, 2025). A common cancer characterized by the presence of malignant glandular cells. "Copy number variants (CNVs) tend to be more prevalent in HAC than in common adenocarcinomas, and CNVs in CCNE1, VSTM2B, PLEKHF1, and POP4 are only present in HAC samples." (PMID 40740864, 2025).
VSTM2B also shares sentences with these, for which no sentence is quoted: breast carcinoma (1 paper); cancer (1); female infertility (1).